IL1B (interleukin 1 beta)
Diseases named in the same sentence as IL1B in open-access papers (continued):
Sharing a sentence is not in itself a finding about the gene and the disease.
gout (continued). "Even though several proinflammatory cytokines and chemokines have been associated with the early phase of acute gouty arthritis, growing evidence derived from experimental and clinical studies indicates a pivotal role for interleukin-1β (IL-1β) in the initiation of inflammation." (PMID 22195044, 2011). "Additionally, chronic inflammation and interleukin (IL)-1β pathways, as well as C-reactive protein, all of which are hallmarks of gout, may be associated with the pathogenesis of CVDs." (PMID 37680887, 2023). "Importantly, the ability of the P2X7 receptor to promote IL-1β secretion upon activation may be a major determinant of gout flares, which is influenced by the gene polymorphisms of the P2X7 receptor." (PMID 34925366, 2021). "An acute episode may be brought about by stimulation of synovial macrophages and monocytes to release large amounts of proinflammatory IL-1β and IL-18, a view that is supported by IL-1 antagonism providing clinical benefit in patients with gout-associated arthritis." (PMID 27562793, 2017). "Gene polymorphisms of TLRs and the NALP3 inflammasome in the signaling pathway stimulated by MSU are related to gout onset, which suggests that the signaling pathway stimulated by MSU may cause more IL-1β secretion in some hyperuricemia patients and increase the risk of gout." (PMID 28797095, 2017). "At the temporal level, acute gout flares are driven by innate immune activation of the NOD-like receptor pyrin domain-containing protein 3 (NLRP3)-interleukin-1β (IL-1β) inflammatory cascade." (PMID 41836392, 2026). "Butyrate has been documented to mitigate the onset of acute gouty arthritis by inhibiting histone deacetylase and curbing the production of IL-1β, IL-6, and IL-8 in response to MSU." (PMID 40696369, 2025). "Once activated, the NLRP3 inflammasome stimulates the secretion of pro-inflammatory cytokines such as IL-1β, which is a key mediator of the characteristic inflammatory cascade in gout." (PMID 40370447, 2025). "Canakinumab, an IL-1β-specific antibody, surpasses conventional treatments in acute gout management, offering extended dosing intervals through a prolonged half-life." (PMID 39861750, 2025). "This pattern of cytokine production shows a functional impact of rs4728141 in gout through altered IL-1β production." (PMID 41155224, 2025). "By day 30, urate crystals were detected in the synovial fluid of the model quails, and the levels of uric acid and inflammatory cytokine IL-1β in synovial fluid were significant increased, indicating the presence of gouty arthritis." (PMID 40771212, 2025). "Although IL-1β has been extensively studied in the pathophysiology of gout, the role of IL-1α remains relatively underexplored." (PMID 40657393, 2025). "This cellular imbalance aligns with the established pathophysiology of gout, characterized by neutrophil recruitment and IL-1β-mediated inflammasome activation triggered by monosodium urate crystals." (PMID 41293160, 2025). "In the 6-h acute gout cell model, expression levels of IL-1β, IL-6, JAK2, STAT1/3 mRNA, and their respective proteins—including phosphorylated JAK2 and STAT1/3—were significantly elevated in the model group compared to the blank control group." (PMID 40170729, 2025). "Given the common inflammatory pathway implicated in gout and ASCVD, we used this unique data set to quantify associations between SU and CV events in the setting of IL-1β blockade." (PMID 39862678, 2025). "In the 2h human blood in vitro gout inflammation model, expressions of IL-1β, IL-6, JAK2 mRNA, and IL-1β, IL-6, JAK2, STAT1/3, p-JAK2, p-STAT1/3 proteins were significantly higher compared to both the blank control and PBS-negative control groups." (PMID 40170729, 2025). "IL-1β, a key inflammatory factor in gout, has been targeted for therapy and can be secreted by various immune cells such as macrophages, neutrophils, and mast cells." (PMID 39968300, 2025).
gout (continued). "Immunohistochemical analysis showed a substantial upregulation in the expression of pro‐inflammatory markers, including TNF‐α, IL‐6, and IL‐1β, in the paw tissues of gout mice compared to the control group." (PMID 39717013, 2025). "This is particularly significant, as IL-1β is considered the main cytokine driving gout inflammation through the activation of the NLRP3 inflammasome." (PMID 40649931, 2025). "The study also showed that there were high levels of mast cell-derived IL-1β in the synovial fluid of gout patients, further confirming that mast cells are involved in the inflammatory response in gout patients." (PMID 40606658, 2025). "Acute flares of gout are marked by IL-1β release, and CHIP has similarly been associated with enhanced IL-1β signaling." (PMID 41516113, 2025). "By day 30, 71% of the model quails displayed MSU deposition in the synovial fluid, along with increased uric acid levels and significant acute inflammatory response (IL-1β significantly increased), effectively simulating the stage of gouty arthritis." (PMID 40771212, 2025). "Consistent with the acute gout model, the Young + Old or Young + Aged group exhibited more pronounced activation of IL-1β, IL-6, and TNF-α in peritoneal fluid and serum." (PMID 39907694, 2025). "In the model group, serum IL-1β levels in quails increased only on day 30 coinciding with the onset of gouty arthritis." (PMID 40771212, 2025). "Tet2-deficient macrophages have shown increased production of proinflammatory cytokines, particularly IL-1β, in murine models of gout and CVD, and TET2 mutations were associated with higher IL-1β levels in the TOPMed study." (PMID 40305610, 2025). "Neutrophils play a major role in mediating inflammation in gout, and IL-1β is a crucial cytokine being released in large quantities from macrophages activated by MSU crystals." (PMID 40791588, 2025). "Mice with gout model supplemented with butyrate showed significant reductions in the foot thickness ratio and the levels of inflammatory factors (IL-1β, IL-6, and TNF-α) in their foot tissue." (PMID 39907694, 2025). "This activation induces the release of pro-inflammatory cytokines, including IL-1β and IL-18, driving the characteristic symptoms of gout attacks." (PMID 40299440, 2025). "Although no significant change in the expression of NLRP3 after supplementation with butyrate was observed in both the gout and peritonitis models, supplementation with butyrate effectively suppressed the production of caspase-1 and IL-1β." (PMID 39907694, 2025). "IL-1β promotes vasodilation, the recruitment of neutrophils, and the production of additional pro-inflammatory cytokines, perpetuating the inflammation in gouty arthritis." (PMID 40352027, 2025). "Activation of the NOD-, LRR- and pyrin domain-containing protein 3 (NLRP3) inflammasome and release of Interleukin-1beta (IL-1β) play critical roles in the inflammatory response in gout." (PMID 39861873, 2025). "Its activation facilitates the release of pro-inflammatory cytokine IL-1β, a key pro-inflammatory cytokine that mediates gout." (PMID 40635741, 2025). "Integrating both components, the PO + MSU model closely reflects the IL-1β-centered pathophysiology of human gout, making it well suited for evaluating interventions with combined urate-lowering and anti-inflammatory potential." (PMID 41515190, 2025). "HUA and gout also increase the risk of bone fragility/fracture because MSU-induced oxidative stress and proinflammatory cytokines (e.g., IL-1β, TNFα, IL-6, IL-8) released by MSU-phagocytosed monocytes, increase bone resorption and decrease bone formation." (PMID 39968300, 2025). "The inflammatory response in gout involves various cytokines such as IL-6, IL-1β, and TNF-α, pivotal in the amplification cascade of inflammation." (PMID 40170729, 2025). "In GA patients, mRNA expression of IL-6, JAK2, STAT1/3, and IL-1β was notably lower in the gout group compared to the healthy control (HC) group." (PMID 40170729, 2025).
gout (continued). "Neutrophils are known to produce IL-1β, a key pro-inflammatory cytokine responsible for initiating acute gout attacks characterized by joint redness, swelling, warmth, and pain." (PMID 41255527, 2025). "The gout flare involves increased production of pro-inflammatory cytokines, mainly IL-1β, by macrophages and monocytes, and the infiltration of neutrophils into affected tissues." (PMID 40710524, 2025). "Recent studies have shown that interleukin (IL)-1β is a key inflammatory mediator in acute gouty arthritis (GA), and its levels are regulated by microRNA (miRNA)." (PMID 41311848, 2025). "IL-1β is a critical proinflammatory cytokine that is responsible for the development of uric-acid-induced sterile inflammatory diseases like gout." (PMID 39065733, 2024). "Activation of the NLRP3 inflammasome also plays a crucial role in the acute symptoms of gout, leading to the release of IL-1β and other pro-inflammatory cytokines." (PMID 38468241, 2024). "Among these, IL-1β is a crucial factor in mediating the inflammatory cascade characteristic of gout." (PMID 39611154, 2024). "Treating wild-type macrophages with a CD11b agonist, LA1, inhibited MSU-induced release of IL-1β in vitro and attenuated the severity of experimental gouty arthritis." (PMID 38863059, 2024). "These novel biomarkers of XOI treatment effects were identified within an interactome with central gout mediators including IL-1B, CXCL8, IL6, and C5." (PMID 39426967, 2024). "The activation of the NLRP3 inflammasome causes the body to produce an abundance of inflammatory factors such as IL-1β, thereby inducing gouty arthritis." (PMID 39544522, 2024). "Canakinumab, an IL-1β inhibitor, has demonstrated significant efficacy in reducing inflammation and preventing acute gout flares, particularly in patients who are intolerant to conventional medications." (PMID 39409183, 2024). "In this study, we aimed to investigate the effect of distilled extracts of ZP, which is known to have anti-inflammatory properties, on IL-1β production and inflammasome signal transduction in gouty arthritis." (PMID 39861092, 2024). "Canakinumab, an IL-1β inhibitor, represents a promising therapeutic option for patients with gouty arthritis, particularly those who are intolerant or unresponsive to conventional therapies." (PMID 39409183, 2024). "The pathogenesis of gouty arthritis is closely related to the body's production of several inflammatory factors such as IL-1β." (PMID 39544522, 2024). "Numerous studies have aimed to find natural remedies that can treat gouty arthritis by regulating IL-1β through targeting the NLRP3 inflammasome." (PMID 39861092, 2024). "Since IL-1β and IL6 have been linked to gout in numerous studies, our main focus was on the connection between CXCL8, CXCL1, and CXCL2 and acute gouty arthritis." (PMID 38686389, 2024). "Compared with those in the group not treated with MSU crystals, RT–qPCR (p=0.0001) and ELISA (p<0.0001) showed that the expression of IL1β was significantly greater and that our gout inflammatory model was successfully established." (PMID 38686389, 2024). "These therapeutic effects are attributed to bioactive compounds, including cucurbitacins, flavonoids, and alkaloids, which inhibit key pro-inflammatory mediators like TNF-α, IL-1β, and IL-6—cytokines involved in the inflammatory response during gout attacks." (PMID 39409183, 2024). "Active caspase-1 is well recognized to cleave pro-IL-1β to produce mature IL-1β in the process of NLRP3 inflammasome activation, which is considered a pathogenic mechanism in the pathogenesis of gout." (PMID 39065733, 2024). "IL-1β prompts immune cell infiltration into damaged tissues, and studies indicate that IL-1β receptor antagonists exhibit promising therapeutic effects on gouty arthritis and GN." (PMID 39170709, 2024).
gout (continued). "MSU crystals have been shown to trigger IL-1β production and inflammatory cytokine release through C5a activation, highlighting the potential of complement antagonists in managing gout inflammation." (PMID 39191722, 2024). "Activation of NLRP3 inflammasome by uric acid monosodium salt crystals and release of IL-1β play a major role in the initiation of gout attacks." (PMID 38376774, 2024). "This activation promotes the caspase-1-dependent maturation and secretion of IL-1β, a critical mediator of the acute inflammatory response in gout." (PMID 39409183, 2024). "Although IL-1β plays a crucial role in the pathogenesis of the pathogenesis of gout flares, other cytokines such as IL-6, TNF-α, and TGF-β are also involved in that." (PMID 38240927, 2024). "Activation of the NOD-like receptor superfamily pyrin domain-containing 3 inflammasome and release of IL-1β play critical roles in the initiation of acute gout flares." (PMID 36896178, 2023). "Here, our results indicated that EA remarkably decreased NLRP3 inflammasome components’ overexpression, including NLRP3, Caspase-1 and IL-1β of gout model animals." (PMID 37464384, 2023). "MCC950 treatment significantly alleviated NLRP3, Caspase-1 and IL-1β protein overexpression in ankle joint tissues of gout model mice compared with vehicle-treated (control) group, confirming the effectiveness of MCC950 on NLRP3 inflammasome." (PMID 37464384, 2023). "MSU can directly stimulate monocytes/macrophages to regulate the release of inflammatory factors such as TNF-α, IL-1β, and IL-18, thereby promoting gout inflammatory response." (PMID 36673346, 2023). "In conclusion, we have demonstrated that upregulated uric acid and IL‐1β levels in the tear fluid of hyperuricemia and gout patients." (PMID 36988248, 2023). "These gout flares are initiated by interleukin (IL)-1β production by macrophages within the synovium." (PMID 36850003, 2023). "Research has demonstrated an elevation in the expression of NLRP3, ASC, IL-1β, and Caspase-1 in joint tissues during the progression of gout." (PMID 38094893, 2023). "Lee’s study showed that oral administration of caffeic acid phenethyl ester (CAPE) suppressed monosodium urate (MSU) crystal-induced caspase-1 activation and IL-1β production in mouse gouty arthritis models." (PMID 37834377, 2023). "We found that dsDNA expression increased during gout remission, while IL-1β, MCP-1, TNF and IL-6 levels decreased significantly." (PMID 37810893, 2023). "The objective of this systematic review was to assess the effects of interleukin-1β (IL-1β) inhibitors on gout flares." (PMID 37491293, 2023). "Rapid IL-1β production by activation of the NLRP3 inflammasome is the characteristic mechanism of the gout inflammatory response." (PMID 38063198, 2023). "Gallic acid is reported to suppress TNF-α and IL-1β levels in gouty arthritis mice model by inhibiting NLR family pyrin domain containing 3 (NLRP3) inflammasome activation." (PMID 36899361, 2023). "This systematic review also provides insights into the effectiveness of IL-1β inhibitors on the occurrence and frequency of gout flares." (PMID 37491293, 2023). "TNF-α, IL-6, and IL-1β are involved in the activation and maintenance of inflammatory responses, which serve key roles in the development and sustenance of gouty arthritis." (PMID 36824696, 2023). "Activation of NLRP3 inflammasome and release of IL-1β by monosodium urate crystals are pivotal pathological factors in gout attacks." (PMID 37370025, 2023). "Recent clinical trials have shown that IL-1β blockade can reduce recurrent attacks of gouty arthritis." (PMID 37881185, 2023). "The NOD-like receptor family, pyrin domain containing 3 (NLRP3) inflammasome can be activated by MSU crystals, resulting in the production of its downstream effectors interleukin (IL)-1β and IL-18 in gout patients." (PMID 36814289, 2023).
gout (continued). "MSU crystals trigger inflammatory vesicles to mediate the production of IL-1β, which mediates inflammation and is a key aspect of gouty arthritis." (PMID 38239361, 2023). "In the present study, the effects of different NLRP3 inflammasome activators on IL-1β secretion were evaluated in vitro using the PBMC-derived macrophages obtained from gout patients." (PMID 36686377, 2023). "In gout, the mature and functional IL-1β production triggered by MSU crystals requires two prerequisite steps, priming and activation (Guo, Callaway & Ting, 2015; So & Martinon, 2017)." (PMID 37197585, 2023). "Based on this finding, several therapies targeting IL-1β demonstrated efficacy in treating gout flares." (PMID 36850003, 2023). "Given that NLRP3 inflammasome activation is a hallmark of AGA, we examined the levels of IL-1β, caspase-1, and NLRP3 in each group of the spontaneous gout rat model." (PMID 36686377, 2023). "The objective of this systematic review was to evaluate the accumulated evidence on the effects of IL-1β inhibitors on gout flares." (PMID 37491293, 2023). "The serum IL-1β and IL-18 levels in the gout patients were significantly higher than in the controls (7.31 ± 11.84 vs. 0.46 ± 0.91, p = 0.004 and 100.51 ± 47.63 vs. 68.49 ± 32.55, p = 0.002, respectively)." (PMID 36979628, 2023). "This modulation aids in alleviating symptoms linked to MSU-induced gouty arthritis, such as neutrophil infiltration in knee joints, joint circumference and the production of TNF-α, IL-1β, IL-6, and IL-18." (PMID 38094893, 2023). "Some human experiments have shown that IL-1β inhibitors rilonacept, canakinumab, and anakinra are effective in the treatment of acute and chronic gout patients." (PMID 37370025, 2023). "Interleukin-1β (IL-1β) plays a pivotal role in mediating gouty inflammation, and its blockade has demonstrated efficacy in combating gout-related pain and inflammation." (PMID 37491293, 2023). "RvD1 can attenuate gouty arthritis pain by reducing leukocyte recruitment and IL-1β production in the knee joint." (PMID 36993950, 2023). "Studies published between 2011 and 2022 that evaluated the effects of IL-1β inhibitors in adult patients experiencing gout flares were eligible for inclusion." (PMID 37491293, 2023). "In our study, plasma cytokines including IL-1β, IL-6 and IL-10 were significantly higher in RA than OA, while TNFα was higher in gout than RA." (PMID 37202736, 2023). "We assessed the inhibitory effects of the R14 peptide in MSU crystals-induced inflammation, with particular emphasized on the production of IL-1β, the master cytokine in gout inflammation." (PMID 37197585, 2023). "Acute gout attacks depend on not only activation of the NLRP3 inflammasome but also upregulation of IL-1β transcription." (PMID 36339582, 2022). "Studies have demonstrated that MSU crystals activate the NLRP3 inflammasome and release IL-1β to play a central role in the initiation of gout attacks." (PMID 36313318, 2022). "Activation of the NLRP3 inflammasome and the subsequent release of IL-1β are critical steps in the initiation of the acute inflammatory response to MSU crystals during a gout flare." (PMID 36064735, 2022). "The activation of the NLRP3 inflammasome and release of IL-1β are thought to be important in the progression of hyperuricemia to gout." (PMID 35464445, 2022). "Downregulation of miR-221-5p significantly promoted the expression of TNFα, IL8, and IL1β during acute gouty arthritis, and IL1β was proved to be targeted by miR-221-5p." (PMID 35812870, 2022). "Mitochondrial dysfunction can induce the NLRP3 inflammasome in gout to promote IL-1β and inflammation." (PMID 35813212, 2022). "Nucleotide-binding oligomerization domain (NOD)-like receptor family pyrin domain-containing 3 (NLRP3) inflammasome-mediated IL-1β production plays a crucial role in the pathological process of gout." (PMID 35047046, 2022).